SALL4 (spalt like transcription factor 4)
Diseases named in the same sentence as SALL4 in open-access papers (continued):
Sharing a sentence is not in itself a finding about the gene and the disease.
tumor (continued). "The master transcriptional factors of MES state cells, such as c-MYC, PRRX1 and NOTCH1 were highly upregulated in the resistant tumor cells, together with the SCP marker S100B and stem cell markers KIT and SALL4." (PMID 40962798, 2025). "Conversely, progesterone receptor (PR) was negative in the only tested case, as well as GATA-3, SALL-4, PTEN, PAX-2, AFP and calretinin, while ARID1A was retained in one case and another tumor has a CK7+/CK20− phenotype." (PMID 39996865, 2025). "SALL4-positive HCC patients exhibit higher HBs antigen positivity and higher levels of tumor markers." (PMID 38584262, 2024). "Investigating the intratumoral distribution of SALL4 in two independent SHH-MB PDXs, we found that SALL4 is detectable in the analysed tumor tissues." (PMID 38062245, 2024). "Proteomic analysis revealed that SALL4 interacts with REN/KCTD11 (here REN), a substrate receptor subunit of the Cullin3-RING ubiquitin ligase complex (CRL3REN) and a tumor suppressor lost in ~30% of human SHH-MBs." (PMID 38062245, 2024). "We found that SALL4 is frequently overexpressed in STAD patients and positively correlated with tumor progression." (PMID 37525212, 2023). "IHC staining for SALL4, LIN28A, and KLF4 was predominantly observed in the epithelial cells of the tumour islands." (PMID 37559082, 2023). "SALL4 expression was increased in STAD and positively correlated with tumor progression and poor prognosis." (PMID 37525212, 2023). "Recent studies have explored novel serum/plasma biomarkers, such as circulating nucleic acids (CNAs), circulating tumor DNA (ctDNA), Glypican-3 (GPC3), and SALL4." (PMID 38173713, 2023). "IHC staining revealed the tumor cells from the liver metastases were immunoreactive for markers including AFP, GPC-3, and SALL4." (PMID 37781207, 2023). "Among the most overexpressed genes in tumor cells compared to normal tissue were the transcription factors HOXB9, SIM2, ZIC5, SP8, TFAP2A, FOXE1, HOXB13, and SALL4; the cancer testis antigen CT83; and the cytokine IL23A." (PMID 37228492, 2023). "Phosphatase and tensin homolog (PTEN) that is an important tumor suppressor gene and blocks Phosphatidylinositol-3-Kinase/Protein Kinase B signaling (PI3K/AKT) is a downstream target of SALL4." (PMID 36010677, 2022). "Consistent with the metastatic tumor cells, the immature neuroectodermal tubules and rosettes in the slide were also diffusely and strongly positive for CD56, SALL4, and OCT-3/4." (PMID 35905234, 2022). "Overall, SALL4 drives tumorigenesis by binding to and transcriptionally activating OXPHOS genes or expressing high levels of SALL4 by blocking OXPHOS to reduce tumor growth, providing novel therapies for HCC." (PMID 35216168, 2022). "Our recent study based on high-throughput chemical screening showed that oligomycin, as well as three other ETC inhibitors, significantly repressed SALL4-expressing HCC cell proliferation and patient-derived HCC xenograft tumor growth." (PMID 36385558, 2022). "The study confirmed that the expression of SALL4 was upregulated in COAD and positively correlated with the degree of tumor differentiation, tumor staging, and metastasis." (PMID 35692499, 2022). "All metastatic tumor cells were diffusely positive for cluster of differentiation (CD) 56 (CD56), Sal-like protein 4 (SALL4), octamer-binding transcription factor-3/4 (OCT-3/4), and vimentin." (PMID 35905234, 2022). "Of note, SALL4, a C2H2 zinc finger TF, correlates with ESC markers of SOX2, OCT4, NANOG, and signaling pathways of BMI-1 and Wnt/β-catenin, leading to control the tumor cell renewal and preserve the pluripotency of ESCs and iPSCs." (PMID 33745265, 2021).
tumor (continued). "We found that there were differences in sex, tumor location, clinical T, N, TNM stage, lymphovascular invasion, nerve invasion, PDL-1 and SALL4 expression between the NAC-first group and the surgery-first group (P<0.1)." (PMID 35083146, 2021). "We further evaluated the correlation between the expression of SALL4 and CD44 using the marker-selected NSCLC cells to initiate in vivo tumor by subcutaneous injection into nude mice." (PMID 29691367, 2018). "We examined the levels of SALL4 expression, PD-1 expression, and CD8+T cell infiltration in the peritumor and center tumor regions of fresh biopsies of HCC patients by immunofluorescent staining." (PMID 29593314, 2018). "In high tumor Hp expression group, EZH2 (r = -0.53, p < 0.001), SALL4 (r = -0.4, p < 0.001), TCF3 (r = -0.45, p < 0.001) were also negatively correlated with Hp." (PMID 28158312, 2017). "Positive staining for pSTAT3 (brown), SALL4 (brown), and SOX2 (brown) was observed in tumor cells and within areas of endothelial proliferation." (PMID 27617262, 2016). "To further investigate the influence of down-regulation SALL4 on tumor growth in vivo, we subcutaneously injected the scramble and shSALL4 TE7 cells into nude mice to establish xenograft tumor models." (PMID 27329034, 2016). "The expression of SALL4 correlated with the expression of OCT4, but inversely correlated with the tumor stage in SqCCs." (PMID 25346886, 2014). "The expression of SALL4 is correlated with the expression of OCT4, but inversely correlated with the tumor stage in SqCCs." (PMID 25346886, 2014). "The expressions of SALL4 and OCT4 were correlated with the tumor differentiation, pathological stage, and patients' clinical information." (PMID 25346886, 2014). "In order to further evaluate the role of SALL4 serum levels in the prognosis of HCC patients, we interrelated the relationship between SALL4 serum concentrations, tumor recurrence, and metastasis, as well as overall survival rate of HCC patients." (PMID 24860834, 2014). "In this study, we investigated the expression of SALL4 and OCT4 using NSCLC tumor tissue microarrays (TMAs) and immunohistochemistry; and correlated their expressions with histological features of tumors and clinical information of patients." (PMID 25346886, 2014). "Recently, Forghanifard and colleagues revealed that stemness state regulators SALL4 and SOX2 are overexpressed in 64 esophageal cancer samples and co-overexpression correlated with depth of tumor invasion and metastasis." (PMID 25114775, 2014). "In advanced tumor stages (stages III and IV), a significant inverse correlation was observed between SALL4 overexpression and the number of involved lymph nodes (P = 0.006, correlation coefficient: -0.737)." (PMID 23363002, 2013). "Cells in IH tumor spheres express GLUT1, indicative of an IH cell of origin, elevated levels of VEGF, and various stem/progenitor cell markers such as SALL4, KDR, Oct4, Nanog and CD133." (PMID 22192404, 2011). "For diagnosis, recognition of the characteristic glandular morphology (the glandular variant being most common) and immunophenotypic expression of markers such as Sal-like protein 4 (SALL4), alpha-fetoprotein (AFP), and glypican-3 is critical for identifying the yolk sac tumor component." (PMID 41425725, 2025). "In this case, the tumor was negative for SALL4 and positive for HepPar-1, suggesting a non-germ cell origin and effectively ruling out YST." (PMID 40919162, 2025). "Rather than promoting tumor formation, Sall4 overexpression led to an expansion of an intermediate LPC-like cell population, characterized by persistent lipid accumulation and dual HNF4A-panCK expression." (PMID 40932240, 2025). "The dual regulation of Sall4 by EZH2 and KDM6A, as observed in tumor progression via the Wnt/β–catenin pathway, may suggest parallel epigenetic mechanisms in the cardiac context that warrant further investigation." (PMID 39936946, 2025).
tumor (continued). "To determine whether Sall4 is required for tumor development in AY-CCA, ANRAS-cHCC-CCA, and KP53-mHCC/CCA models, we conditionally deleted Sall4 in HCs—cells in which oncogenes are hydrodynamically delivered to induce tumors." (PMID 40932240, 2025). "Despite this reduction, the remaining tumors were still panCK+ but HNF4A−, indicating that Sall4 deletion does not alter tumor cell fate but inhibits CCA tumor expansion." (PMID 40932240, 2025). "Immunohistochemically, the tumor was positive for SALL4 and negative for CD30, AFP, OCT3/4, PLAP, D2‐40, and hCG." (PMID 41185737, 2025). "While SALL4 genetic depletion or MGCD0103 treatment alone restrains tumor cell proliferation, their combination does not further induce the inhibition of SHH-MB cells proliferative capability." (PMID 38062245, 2024). "The activated pluripotency transcriptional network, consisting of SALL4/OCT4/DPPA2/Nanog in CRC, plays essential roles in the maintenance of the stemness state, self-renewal characteristics, and progression of tumor cells, leading to an increased depth of invasion." (PMID 38584262, 2024). "As a tumor suppressor, PTEN (phosphatase and tensin homolog) is considered a target gene of SALL4." (PMID 38584262, 2024). "Whereas cells infected with the lentiviral particles expressing a non-targeting sequence (shCTR) give rise to detectable tumor masses, cells in which SALL4 has been silenced do not grow." (PMID 38062245, 2024). "Overall, these data confirm the relevance of SALL4 in SHH-MB growth and tumor prognosis." (PMID 38062245, 2024). "By analyzing gene expression patterns and conducting clinicopathological tests on tumor and adjacent tumor-free tissues from 50 ESCC patients, researchers have shown that SALL4 expression positively correlates with that of MEIS1, a homeobox transcription factor." (PMID 38584262, 2024). "These round tumour cells were rich in clear cytoplasm and positive for Oct4, SALL4, PLAP and CD117 and negative for CK, CEA, CD30 and SOX2." (PMID 37118812, 2023). "Among the most overexpressed genes in tumor cells compared to normal tissue are genes coding for transcription factors (HOXB9, SIM2, ZIC5, SP8, TFAP2A, FOXE1, HOXB13, and SALL4), cancer testis antigens (CT83), and cytokines activating regulatory Th17 cells (IL23A)." (PMID 37228492, 2023). "Beyond the tumour area, inside the remnant thymus tissues, there were small clusters of polygonal tumour cells with clear cytoplasm, distinct cell membranes, and round to polygonal nuclei with prominent nucleoli that were positive for Oct4, PLAP, SALL4 and CD117." (PMID 37118812, 2023). "Immunohistochemically, tumor cells are positive for stem/progenitor cell markers, such as CK 19, EpCAM, cluster of differentiation 56 (CD56), CD117, and spalt-like transcription factor 4 (SALL4)." (PMID 37761023, 2023). "SALL4 silencing resulted in PTEN upregulation, which inhibited PI3K/AKT signaling, indicating that PTEN is a critical functional downstream target of SALL4 in tumor development." (PMID 35216168, 2022). "Interestingly, squamous cell markers such as SALL4, NANOG, SOX2, BMI1, OCT3/4, HIWI, ABCG2, CD133, podoplanin, and ALDH1 also correlate with ESCC tumor stages, therapeutic resistance, relapse, and patient prognosis." (PMID 36474162, 2022). "Expectedly based on these data, our experiment on SOC tissue samples demonstrated higher expression of SALL4 in tumor tissues rather than normal tissue samples while the expression of ALDH1A1 protein reduced in tumor tissues in comparison to normal tissues." (PMID 35090523, 2022). "Most cancer studies relate SALL4 to an oncogenic function and SALL1–3 to a tumor suppression role; still, there is evidence that SALL1 and SALL2 could play a dual role." (PMID 34944911, 2021). "Considering the prognostic role of LINC-ROR, its function in tumor progression, and its correlation with stemness markers, a probable correlation may be existed between the expression of LINC-ROR and SALL4 in tumorigenesis." (PMID 33745265, 2021).
tumor (continued). "Further analyses of the correlations between the breadth of the T cell response, i.e., the number of CTA, SALL4 and AFP being recognized, and the tumour stage and other tumour characteristics were performed according to the distinct profile of the tumour antigen-specific T cell response." (PMID 34496797, 2021). "Cluster formation was significantly increased in ALDH1-positive/SALL4-negative samples, suggesting that such tumor cells contain a subpopulation with a greater capacity for cluster formation." (PMID 34441397, 2021). "As exhibited by immunohistochemistry, the positive rates of SALL4, MMP-2, MMP-9, and PCNA proteins were decreased in tumor tissues of mice treated with exosomes, and these trends were further facilitated in the tumor tissues of mice treated with miR-15a agomir-exos." (PMID 34455417, 2021). "Heterozygous Sall4+/− cko mice displayed no phenotype in comparison to control animals in regard to primary tumor numbers." (PMID 34417458, 2021). "First, SALL4 regulates the self-renewal of cancer stem cells by targeting a variety of genes, such as upregulation of Bmi-1, Wnt/β-catenin and HoxA9 and repression of PTEN, a tumor suppressor gene." (PMID 32098783, 2020). "Tumor cells were positive for epithelial membrane antigen (EMA) and vimentin and focally positive for CD99, HHF-35, desmin, calponin, and Sal-like protein 4 (SALL4)." (PMID 33176817, 2020). "Similar to the immunostaining results of tumor tissues from BC patients, TFCP2L1‐expressing cells in xenograft samples showed a high concurrence with cells stained with the bladder CSC markers including CD44, KRT14, and SALL4." (PMID 31709755, 2020). "SALL4 plays diverse roles in tumor growth, metastasis, and drug resistance, but its role in tumor metabolism has not been well characterized." (PMID 32489324, 2020). "Because the JNK pathway is an essential pathway driving tumor growth and invasion, we investigated whether the JNK pathway mediates sal/SALL4 overexpression-induced cell invasion." (PMID 32098783, 2020). "This tumor showed positivity for AFP, GLP3 and SALL4, and negativity for CK7 and EMA." (PMID 32493368, 2020). "SALL2 and SALL4 are positive regulators of PTEN and can regulate tumor metastasis." (PMID 32707933, 2020). "In this report, we found that SALL4 significantly correlates with the levels of MMPs and TIMPs which are related to tissue remodeling and tumor invasiveness, thus suggesting a potential mechanism for SALL4-mediated metastatic behavior without EMT involvement." (PMID 32513235, 2020). "SALL2 and SALL4 have been recently recognized as regulators of tumorigenesis, but little information is known about the role of the SALL1 gene in regulation of tumor biology." (PMID 29625565, 2018). "Immunohistochemically, the tumor cells were positive for AFP, GPC3, and SALL4." (PMID 30228922, 2018). "Further, statistics analysis showed that there was a positive correlation between SALL4 expression and tumor infiltrating PD-1+CD8+T cells, raising a possibility that hepatocyte SALL4 involves PD-1+CD8+T cell exhaustion via expressing PD-L1 during HBV+HCC progression." (PMID 29593314, 2018). "SALL4 blood copy numbers were conversely correlated with tumor depth of invasion, cases without tumor invasion into the adventitia had significantly higher levels of SALL4 copy numbers compared with patients with tumor invasion." (PMID 30579343, 2018). "In contrast, transfection with SALL4 or control vector in these tumor cells did not induce increased SA-β-Gal expression." (PMID 29625565, 2018). "Real time PCR (RT-PCR) allows a precise quantification of SALL4 expression, although this method can be affected by tumor heterogeneity and it does not provide any information about the subcellular localization of SALL4." (PMID 28160555, 2017). "The stemness markers SALL4 and NANOG were strongly expressed in tumor spheres." (PMID 28620148, 2017).
tumor (continued). "Taken together, our results indicate that SALL4 expression is closely correlated with tumor stage, lymph node metastasis and poor survival in ESCC patients." (PMID 27329034, 2016). "The overexpression of SALL4 of hepatocytes was correlated with a more aggressive subtype of HCC and poor prognosis, such as tumor recurrence, tumor size, multiplicity, vascular invasion, pathological tumor stage, and overall survival rate." (PMID 27610139, 2016). "The results of tumour growth curve and tumour weight showed that SALL4 knockdown significantly retarded the growth of xenograft tumours in mice; however, the simultaneous overexpression of CD44 greatly accelerated xenograft tumour growth." (PMID 27819668, 2016). "We found that the expression of SALL4 has no relation with any of the clinicopathologic characteristics assessed (age, sex, histologic grade, tumor locality, vascular invasion, tumor size, nodal metastasis, TNM stage, and so on)." (PMID 24860834, 2014). "We examined the expression of SALL4 and OCT4 in NSCLC tumor tissue using TMA and IHC stains." (PMID 25346886, 2014). "We compared SALL4 mRNA expression in 46 tumor specimens to their paired non-neoplastic colorectal epithelium by quantitative real time-PCR." (PMID 23363002, 2013). "The genes SALL4 and TM4SF5 were expressed to a higher extent in the tumours from deceased patients in our material and have been reported to be up-regulated in other cancers, and may thereby represent putative oncogenes." (PMID 18778486, 2008). "Given that SALL4 is largely absent in normal adult tissues, therapies against SALL4 might achieve tumor specificity, an aspect further discussed in later sections." (PMID 41163374, 2025). "Tumor sphere assays evaluation revealed the remarkable reduction the sphere-forming ability of CD44( + )-OSCC cells following METTL3 knockdown, which could be partially reversed it by SALL4 overexpression." (PMID 38355684, 2024). "The binding of malignancy factor Sal-like 4 (SALL4) to RBBP4 is similar in that the large and shallow acidic interaction surface of RBBP4 binds to 5 basic residues of SALL4, resulting in the interaction of SALL4 with NuRD and subsequent repression of tumor suppressor transcripts." (PMID 38028543, 2023). "While this may reflect germ cell remnants present within these regions, SALL4 staining was low/absent, therefore the significance of these results in the context of the tumours is currently unclear." (PMID 37564373, 2023). "Therefore, the co-expression of SALL4 and LIN28A in AME observed in this study may play a significant role in tumour pathogenesis." (PMID 37559082, 2023). "However, CK8, S-100 and SALL-4 that stained positive in the primary tumor were negative in TCS627 cells." (PMID 38201285, 2023). "Decreased SALL4 expression leads to decreased cellular viability and increased apoptosis in vivo consistent with known effect of SALL4 on the expression of oncogenes and tumor suppressor genes, but the study did not further investigate the downstream effectors of SALL4 in this context." (PMID 34573282, 2021). "CTA- and SALL4-specific T cell responses may be important for controlling HCC in the early stage, whereas AFP-specific T cell responses might be a signature of malignant tumour status in the advanced stage." (PMID 34496797, 2021). "Furthermore, a correlation of MEIS1 and SALL4 was found in tumor samples without metastasis, compared to metastasized ESCCs." (PMID 32819319, 2020). "SALL4 is an ESC marker that plays a role in multiple cancer types by regulating proliferation, apoptosis, chemoresistance, and maintenance of CSCs, as well as modulating expression of pSTAT3, which is required for tumor formation, growth, and suppression of apoptosis." (PMID 28321397, 2017). "Since SALL4 mRNA expression is significantly correlated with metastasis of tumor cell to lymph node in CRCs, it may be remarkable that 83.3% of samples without SALL4 overexpression (5 of 6) have not showed metastasis to lymph node." (PMID 23363002, 2013).